WNT3A (Wnt family member 3A)
Diseases named in the same sentence as WNT3A in open-access papers (continued):
Sharing a sentence is not in itself a finding about the gene and the disease.
melanoma (37 papers, 2009 to 2026). A malignant, usually aggressive tumor composed of atypical, neoplastic melanocytes. "In fact, stimulation of melanoma cells with WNT3a induced the expression of genes associated with differentiation but suppressed genes with a function associated with proliferation." (PMID 36612190, 2022). "We demonstrated that loss of function of FAM129B inhibits the apoptosis of melanoma cells induced by the combined treatment with WNT3A and PLX4720." (PMID 24358901, 2013). "In cultured melanoma cells treated with long-term BRAFi, activation of Wnt/β-catenin signaling is markedly inhibited, coinciding with a loss of the enhancement of BRAFi-induced apoptosis by WNT3A observed in BRAFi-naïve cells." (PMID 24733413, 2014). "For example, Wnt1 and Wnt3a promote melanocyte differentiation and melanoma development via β-catenin-dependent signaling." (PMID 38388496, 2024). "It has been revealed that a morin-induced overexpression of miR-216a in CD133+ melanoma subpopulation inhibited WNT3A expression through miR-216a, which directly targets WNT3A 3′-UTR." (PMID 39684513, 2024). "Whereas Wnt-3a treatment induced an efficient translocation of β-catenin to the nucleus of the proliferative melanoma cells, TGFβ treatment also relocalized β-catenin to the nucleus, although to a lesser extent." (PMID 34819356, 2022). "To this end, we treated proliferative M000921 and M010817 patient-derived melanoma cells with either recombinant human TGFβ or with recombinant murine Wnt-3a, or we knocked down LATS1 and LATS2 to induce the transcriptional activity of YAP/TAZ." (PMID 34819356, 2022). "A drop in Axin1 levels was also observed to precede and be independent of apoptosis onset, significantly inhibiting tumor growth in melanoma mouse models induced by WNT3A and PLX4720." (PMID 34577571, 2021). "On the other hand, the effect of an inhibition of BRAF-mediated signaling in melanoma was studied by co-administering WNT3A and PLX4720 (a BRAFV600E inhibitor)." (PMID 34577571, 2021). "In one study, when a melanoma cell line was treated with wnt3a, CTLA4 was the most up-regulated gene, which was proposed to represent a mechanism of immune evasion." (PMID 32835228, 2020). "Wnt3a or small-molecule activators of β-catenin signaling reduce the proliferation in B16 melanoma cells and other human melanoma cell lines in vitro." (PMID 30719233, 2019). "B16 melanoma cells overexpressing Wnt3a also have decreased tumor size and metastasis when cells are implanted into mice." (PMID 30719233, 2019). "Further stratification of the WNT3Ahigh and WNT3Alow melanoma tumors by their PTEN expression levels yielded a reduced five-year overall survival (OS) for patients with high WNT3A and low PTEN expression levels." (PMID 29454361, 2018). "Treatment of four different melanoma cell lines with Wnt3a-CM induced AXIN2 expression in comparison with 3T3-CM treated melanoma cells." (PMID 29454361, 2018). "In the present study, we demonstrate a novel role of Wnt3a and the β-catenin signaling pathway in neural crest migration and malignant invasion of human melanoma cells." (PMID 29454361, 2018). "Fibroblast derived Wnt3a reduced melanoma cell adhesion and enhanced migration, while the β-catenin inhibitor PKF115–584 increased adhesion and reduced migration in vitro and in the chick embryonic neural crest environment in vivo." (PMID 29454361, 2018). "RNA expression analyses of melanoma cells pre-conditioned with either Wnt3a or PKF115–584, and of zebrafish embryo neural crest cells demonstrated overlapping genes." (PMID 29454361, 2018). "On protein level the treatment of melanoma cells with Wnt3a-CM increased β-catenin expression whereas PKF115–584 treatment reduced β-catenin as expected." (PMID 29454361, 2018). "Before injection, the melanoma cells were pre-conditioned with either the agonist Wnt3a or with the β-catenin-inhibitor PKF115–584." (PMID 29454361, 2018).
melanoma (continued). "We find that itraconazole increases Gli-3, Axin-1 expression but decreases Gli-1, Gli-2, Axin-1, β-catenin, Wnt3A and Cyclin D1 expression in both melanoma cell lines when compared with untreated cells." (PMID 28212537, 2017). "To confirm this, we analyzed the amount of cells committed to apoptosis through annexin V staining and found that WNT3A-activated signaling significantly increased apoptosis in melanoma cells." (PMID 28092677, 2017). "Given the previously identified role of WNT signaling in regulating cancer metabolism, we decided to investigate the bioenergetic properties of PTENWT and PTENMut melanoma cells in response to WNT3A signaling." (PMID 28092677, 2017). "This led us to the intriguing observation that in PTENWT melanoma cells in response to WNT3A, the mitochondria amassed in dense peri-nuclear clusters, which was not apparent in the PTENMut cells." (PMID 28092677, 2017). "Overall, these findings indicate that melanoma cells expressing high levels of PTEN respond to WNT3A signaling with metabolic reprogramming and mitochondrial remodeling, which is dependent upon β-catenin activity." (PMID 28092677, 2017). "Taken together, these finding show that β-catenin signaling is essential for mitochondrial remodeling induced by WNT3A, but also for the WNT3A-mediated bioenergetic reprogramming of PTENWT melanoma cells." (PMID 28092677, 2017). "Taken together, these data show that melanoma cells respond to WNT3A signaling with differing metabolic signatures based on PTEN expression, which for the PTENWT cells results in significantly reduced cellular metabolism." (PMID 28092677, 2017). "We therefore examined the effects of transient knockdown of β-catenin in PTENWT WNT3A overexpression melanoma cells using small interfering RNA (siRNA) and found efficient reduction of CTNNB1 gene expression in response to treatment." (PMID 28092677, 2017). "Findings from our reporter assay experiments suggest that in melanoma cells, WNT3A is signaling in a β-catenin-dependent manner." (PMID 28092677, 2017). "Higher power images of mitochondrial regions in PTENWT melanoma cells in response to forced WNT3A signaling showed that the mitochondria appeared to be elongated in shape compared with the control cells." (PMID 28092677, 2017). "This has been further corroborated by analyzing LC3 punctae staining in the presence of an autophagy inducer and found that WNT3A can significantly reduce autophagosome function in PTENWT melanoma cells." (PMID 28092677, 2017). "Wnt5a signaling activates the PI3K-AKT pathway in melanoma cells and Wnt3a-induced proliferation involves activation of ERK beside Wnt/β-catenin pathway activation in fibroblasts." (PMID 27323822, 2016). "Of significance are the melanoma-related genes NOTCH1, NOTCH2, WNT3a, and WNT5a, each of which are associated with two or more UV-miRNAs that can directly target these respective genes." (PMID 27149382, 2016). "Addition of micromolar concentrations of Riluzole, a putative glutamate receptor antagonist (GRM1) enhanced Wnt/β-catenin signaling, shown to decrease proliferation and increase the differentiation of melanoma cells in vitro when combined with exogenous Wnt3a." (PMID 25915038, 2015). "The protein kinase N1 inhibits Wnt/β-catenin signaling and sensitizes melanoma cells to cell death stimulated by Wnt3a." (PMID 26369691, 2015). "For instance, the elevated WNT3A promotes the growth of myeloma cells in vitro and prostate tumor in mouse model, while it dramatically decreases the growth of melanoma cells transplanted in the mice." (PMID 24564888, 2014). "In the present study, we applied this technology to advance our understanding of the responses of melanoma cells to signaling initiated by the secreted ligand WNT3A." (PMID 24114839, 2013). "We observed that cells transfected with siRNAs targeting PKN2 exhibit increased WNT3A-dependent activity of the BAR in A2058 melanoma cells (lane 2)." (PMID 24114839, 2013).
melanoma (continued). "Following treatment of A375 melanoma cells with WNT3A, phosphorylation sites on CTNNB1 typically regulated by GSK3 become dephosphorylated, and as CTNNB1 accumulates, those sites are again phosphorylated (time course in lanes 1–4)." (PMID 24114839, 2013). "Co-treatment of melanoma cell lines with WNT3A-conditioned media and recombinant TRAIL significantly enhanced apoptosis compared to treatment with TRAIL alone." (PMID 23869245, 2013). "WNT3A treatment significantly enhanced TRAIL-dependent apoptosis in multiple melanoma cell lines, but did so in a heterogeneous fashion with some lines being unaffected by WNT3A in terms of TRAIL sensitivity." (PMID 23869245, 2013). "We stimulated duplicate cultures of A375 human melanoma cells with WNT3A for two periods of time to activate β-catenin signaling at the level of the receptors." (PMID 24114839, 2013). "We have shown previously that co-treatment of several melanoma cell lines with WNT3A and with a targeted BRAF-V600E inhibitor synergistically increases Wnt/β-catenin signaling and apoptosis." (PMID 24114839, 2013). "We therefore examined levels of several known or predicted regulators of TRAIL dependent-apoptosis in melanoma cells treated with WNT3A CM in the presence of the pan-caspase inhibitor zVAD-FMK." (PMID 23869245, 2013). "We therefore tested a panel of melanoma cell lines for their sensitivity to rhTRAIL in the presence of WNT3A." (PMID 23869245, 2013). "In the present study we demonstrate that FAM129B promotes Wnt/β-catenin signal transduction in melanoma cells and that reducing levels of FAM129B with siRNA reduces the ability of WNT3A to increase apoptosis in melanoma cells." (PMID 24358901, 2013). "To advance the characterization of changes in protein phosphorylation upon stimulation of the Wnt/β-catenin pathway, in the present study, we defined the WNT3A-regulated phosphoproteome in a melanoma cell line." (PMID 24114839, 2013). "The degree by which WNT3A enhances sensitivity to TRAIL is heterogeneous among different melanoma cell lines." (PMID 23869245, 2013). "Given thatFAM129B silencing inhibits Wnt/β-catenin target gene expression and apoptotic response to WNT3A, we sought to determine ifFAM129B expression levels predict Wnt/β-catenin pathway activation in patient melanoma samples." (PMID 24358901, 2013). "Previously, we have shown that melanoma cells undergo programmed cell death following continuous treatment with WNT3A." (PMID 24114839, 2013). "We conclude that depletion of PKN1 increases WNT3A-dependent cell death in A375 and Mel-624 melanoma cells." (PMID 24114839, 2013). "Because reducing expression of PKN1 and PKN2 elevates Wnt/β-catenin-dependent transcription, we predicted that PKN depletion would promote WNT3A-dependent melanoma cell apoptosis." (PMID 24114839, 2013). "We have previously shown that WNT3A can activate β-catenin-dependent transcription and inhibit the proliferation of some melanoma cell lines." (PMID 23129487, 2012). "In contrast, our previous results using established murine and human melanoma cell lines indicate that activating WNT/ß-catenin signalling with WNT3A can inhibit the growth of melanoma cells in vitro and in vivo." (PMID 23129487, 2012). "Interestingly, in melanoma, the induction of Wnt3a led to reduced proliferation in vivo and decreased tumor size due to the activation of Wnt/β-catenin." (PMID 38388496, 2024). "Hierarchical clustering analysis using the Widmer and the Verfaillie gene sets confirmed that Wnt-3a treatment promoted the proliferative, differentiated melanoma cell phenotype, whereas TGFβ and siLATS1/2 treatment induced an invasive phenotype with a dominant effect over Wnt-3a treatment." (PMID 34819356, 2022).
melanoma (continued). "To investigate the effect of TGFβ-, siLATS1/2–, and Wnt-3a–mediated signaling on melanoma phenotypes on a global level, we next performed gene set enrichment analysis using publicly available gene sets characterizing the proliferative or invasive melanoma cell state." (PMID 34819356, 2022). "In addition, a majority of β-catenin-binding proteins in PTENwt A375-P melanoma cells are involved in metabolic processes, which are vastly altered by Wnt3A-mediated signaling." (PMID 33647315, 2021). "The down-regulation of INHBA, CYR61 and ANGPTL4, which was found in SKMEL28 melanoma cells after treatment with Wnt3a-CM could be confirmed in these four cell lines by real-time qPCR when compared to the 3T3-CM samples." (PMID 29454361, 2018). "Together, our results show a novel role of Wnt3a/β-catenin signaling in melanoma cell neural crest like migration and invasion and suggest the participation of β-catenin during active melanoma cell invasion into the dermal matrix, the brain microcompartment and during metastasis to the liver." (PMID 29454361, 2018). "Going back to embryologic neural crest induction, we asked in this project whether the Wnt3a/β-catenin signaling pathway was also directly involved in melanoma cell adhesion/migration in vitro and in vivo in an embryonic micro-environment of the neural crest." (PMID 29454361, 2018). "Given that this is consistent with previous findings, we hypothesized that the novel metabolic and mitochondrial effects we have noted in PTENWT melanoma cells in response to WNT3A signaling, is dependent upon β-catenin activity." (PMID 28092677, 2017). "Wnt3a enhances TRAIL-dependent apoptosis in multiple melanoma cell lines." (PMID 26369691, 2015). "Moreover, treatment with WNT3A-containing conditioned media or stable overexpression of WNT3A in mouse B16 or human A375 melanoma cells reduces cell numberin vitro." (PMID 24358901, 2013). "Thus, our results demonstrate that depletion of PKN1 can synergize with WNT3A stimulation to promote apoptosis in malignant melanoma cells, and this effect requires CTNNB1." (PMID 24114839, 2013). "We also demonstrate that FAM129B knockdown inhibits apoptosis in melanoma cells treated with WNT3A." (PMID 24358901, 2013). "Additionally, B16 melanoma cells expressing WNT3A implanted into mice exhibit decreased tumor size and decreased metastasis." (PMID 24416617, 2013). "Furthermore, WNT3A overexpression in mouse or human melanoma cell lines inhibits in vitro proliferation and in vivo tumor growth." (PMID 23869245, 2013). "Moreover, WNT3A upregulates genes involved in melanocyte differentiation, several of them are downregulated with melanoma progression." (PMID 24416617, 2013). "FAM129B siRNAs suppress apoptosis in melanoma cells treated with WNT3A and PLX4720." (PMID 24358901, 2013). "Interestingly, Riluzole treatment upregulates the Wnt3a expression in melanoma cells in vitro, and enhances the Wnt/β-catenin signaling in both HT22 neuronal cells and adult hippocampal progenitor cells 82, 83, suggesting that Riluzole is an enhancer of the Wnt/β-catenin signaling." (PMID 40860154, 2025). "However, we detected an increased number of single and clustered SKMEL28 melanoma cells along distal sites of the medial neural crest cell pathway close to the notochord and the developing para-aortic sympathetic ganglia upon Wnt3a stimulation (p = 0.0152, Fisher’s Exact Test)." (PMID 29454361, 2018). "Interestingly it has previously been reported that in melanoma, depending on the cell line used, β-catenin signaling can either enhance or reduce cell invasion, therefore we investigated the effects of WNT3A on the invasive capacity of our panel of melanoma cells." (PMID 28092677, 2017).
melanoma (continued). "To test whether the observations made using the XFe96 analyzer were due to differences in the way PTENWT and PTENMut melanoma cells respond bioenergetically to WNT3A signaling, we analyzed metabolic responses to rWNT3A stimulation/WNT3A overexpression in the whole panel of melanoma cells." (PMID 28092677, 2017). "Additionally, transcriptional profiling revealed that Wnt3A may exert these effects by its ability to upregulate markers of differentiation in melanoma, similar to its function during initial melanocyte development." (PMID 24281103, 2010). "First, CRISPR activation screens in melanoma cells identify functionally diverse regulators of TCR-specific cytotoxicity, including SAFB, KHDRBS1, MYC, CD44, WNT3A, WNT1 and others." (PMID 41946842, 2026). "Using the overexpression melanoma cells, we found that both OCR and ECAR rates were altered in response to WNT3A signaling, which interestingly differed between the PTENWT and PTENMut lines." (PMID 28092677, 2017). "In the present study we find that itraconazole can decrease Wnt3A and β-catenin by changing transcription and protein levels in A375, SK-MEL-28, SK-MEL-2 and Malme-3M melanoma cells." (PMID 28212537, 2017). "LY294002 blocks WNT3A-mediated increased cell migration in A2058 cells, demonstrating that the effect of WNT/β-catenin signaling on melanoma cell motility is PI3K-dependent." (PMID 28092677, 2017). "The combined treatment with WNT3A protein and compounds that inhibit ERK/MAPK signaling synergizes to induce robust apoptosis in cultured melanoma cells." (PMID 24358901, 2013). "Unexpectedly, the depletion of AXIN1 significantly sensitized all melanoma cell lines to TRAIL, even those in which WNT3A was insufficient to sensitize cells to rhTRAIL." (PMID 23869245, 2013). "To determine the effect of AXIN1 depletion on TRAIL-mediated apoptosis, we pre-treated melanoma cell lines with siRNA specific for AXIN1 prior to treatment with TRAIL and WNT3A CM." (PMID 23869245, 2013). "Collectively, these results show that FAM129B is required for the synergy between Wnt3A and PLX4720 to induce melanoma apoptosis." (PMID 24358901, 2013). "After WNT3A stimulation, we found that AXIN2 transcripts increased in abundance in cells transfected with PKN siRNAs in all melanoma cell lines tested." (PMID 24114839, 2013). "Of note, changes in β-Catenin dependent (WNT3A driven) as well as β-Catenin independent (WNT5A driven) Wnt signaling (canonical versus non-canonical) have been described in the context of cancer and melanoma." (PMID 39562548, 2024). "JQ1 was characterized by induction of inhibitory relationship linking regulators of inflammation (IFNG, IL17A, TGFB2), melanoma biological behavior (EGFR, WNT3A, TEADs, MRTFB), cell-cell interaction (CD44, CCN2), YAP pathway (LLGL2, NSUN6) and main transcriptional regulators (FOS, JUN, FOXM1)." (PMID 36397155, 2022). "Treating WNT3A-expressing melanoma spheroids with PLX4720 led to a decrease in spheroid size and in the number of invasive cells with respect to PLX4720-treated, GFP-derived spheroids or DMSO-treated, WNT3A-derived spheroids." (PMID 34577571, 2021). "This is further substantiated by the bad impact of low PTEN expression levels on melanoma patient survival in the context of a high expression of WNT3A (whereas PTEN levels have no impact on survival for WNT3A low melanomas)." (PMID 29454361, 2018). "As expected, treatment of the SKMEL28 melanoma cells with Wnt3a-conditioned medium but not with 3T3-conditioned medium induced the transcriptional activity of the Wnt/β-catenin signaling pathway." (PMID 29454361, 2018). "As expected nor did we see an effect of WNT3A signaling on mitochondrial content in PTENMut melanoma cells." (PMID 28092677, 2017). "Using this β-catenin knockdown approach, we began to evaluate whether we could confirm some of our previous findings made using hyperactive WNT3A signaling, starting with cell migration in the PTENWT melanoma cells." (PMID 28092677, 2017).